LAMA1 (laminin subunit alpha 1)
Diseases named in the same sentence as LAMA1 in open-access papers (continued):
Sharing a sentence is not in itself a finding about the gene and the disease.
LAMA1 also shares sentences with these, for which no sentence is quoted: developmental delay (3 papers); myopathy (3); brain disease (2); ciliopathies (2); Congenital muscular dystrophy type 1A (2); Anxiety (1); astrocytoma (1); Ataxia (1); Autoimmunity (1); Bardet-Biedl syndrome (1); basal cell carcinoma (1); cataract (1); Cerebellar hypoplasia (1); cerebellar malformation (1); colitis (1); conduction disorders (1); degenerative diseases (1); dementia (1); Dent disease (1); depression (1); Duchenne muscular dystrophy (1); Dystonia (1); E. coli infection (1); epilepsy (1); Hyperglycemia (1); keratoconus (1); legionellosis (1); lung carcinoma (1); lymph node metastasis (1); metastatic cancer (1).
A further 23 diseases each share a sentence with LAMA1 in 1 paper.